ANOS1 (anosmin 1)
Description:
Has a dual branch-promoting and guidance activity, which may play an important role in the patterning of mitral and tufted cell collaterals to the olfactory cortex (By similarity). Chemoattractant for fetal olfactory epithelial cells.
Synonyms: ADMLX; KAL; KAL1; KALIG-1; WFDC19; HH1; HHA; KMS
Tractability: Antibody: UniProt places it where antibodies can reach, with high confidence; its Gene Ontology location is reachable by antibodies, with high confidence; UniProt predicts a signal peptide or a membrane-spanning region.
Gene: Protein-coding gene on chromosome X (8,528,874 to 8,732,195, reverse strand). Ensembl gene ENSG00000011201.
Subcellular location: Cell membrane; Secreted
Pathways (Reactome):
Signal Transduction: FGFR1c ligand binding and activation; Negative regulation of FGFR1 signaling
Gene Ontology:
Molecular function: protein binding; peptidase inhibitor activity
Biological process: axon guidance; cell adhesion; chemotaxis; neuron differentiation
Cellular component: extracellular region; cell surface; plasma membrane
Gene-disease validity (ClinGen):
ClinGen rates the evidence that ANOS1 causes each of these diseases.
hypogonadotropic hypogonadism 1 with or without anosmia (X-linked): Definitive. The X-linked inherited form of Kallmann syndrome caused by mutation of the KAL1 gene mapped to chromosome Xp22.3.
Homologues: Orthologues: chimpanzee ANOS1 (99% identical), macaque ANOS1 (98% identical), dog ANOS1 (84% identical), guinea pig ANOS1 (81% identical), tropical clawed frog anos1 (73% identical), zebrafish anos1a (53% identical), zebrafish ANOS1 (33% identical), Caenorhabditis elegans kal-1 (24% identical), Drosophila melanogaster Kal1 (20% identical).
Diseases named in the same sentence as ANOS1 in open-access papers:
ANOS1 is named in the same sentence as 88 diseases in open-access papers, as found by Europe PMC text mining. Sharing a sentence is not in itself a finding about the gene and the disease. The quoted sentences say what the papers report.
Kallmann syndrome (66 papers, 2004 to 2025). Kallmann syndrome (KS) is a developmental genetic disorder characterized by the association of congenital hypogonadotropic hypogonadism (CHH) due to gonadotropin-releasing hormone (GnRH) deficiency, and anosmia or hyposmia (with hypoplasia or aplasia of the olfactory bulbs). "Evidence has indicated that mutations in the ANOS1 gene are linkedto significant clinical manifestations such as anosmia and hypogonadism." (PMID 41165467, 2025). "Affected males carrying the ANOS1 mutations displayeda range of phenotypes, all of which were associated with hypogonadism andvarying degrees of anosmia." (PMID 41165467, 2025). "In humans, loss of function of ANOS1 causes neuronal migration defects that result in Kallmann syndrome, but a microduplication that causes overexpression of ANOS1 also seems to cause disease." (PMID 40901950, 2025). "In the reported cases, males with the ANOS1 mutation exhibitedseveral classic features of KS, including anosmia, delayed puberty, andcryptorchidism." (PMID 41165467, 2025). "The glycoprotein called “Anosmin-1”, encoded by the KAL1 gene, is defective in human Kallmann syndrome." (PMID 38612730, 2024). "A1 is encoded by the ANOS1 gene, former KAL1, whose mutation produces the Kallmann syndrome (KS) that is characterized by hypogonadotropic hypogonadism and anosmia, presumably as a result of defects in neuronal migration and axonal targeting." (PMID 36995433, 2023). "Missense and frameshift mutations in the KAL1 or ANOS1 gene located in the X chromosome are responsible for 8% of all known genetic mutations of Kallmann syndrome." (PMID 37294556, 2023). "In Kallmann syndrome, anosmia/hyposmia is part of the clinical picture, and ANOS1, CHD7, FGFR1, PROK2, PROKR2, and SEMA3A variants were reported to be involved in isolated congenital anosmia." (PMID 32222824, 2021). "Kallmann syndrome caused by ANOS1 gene mutations is inherited by X-linked recessive trait as it is located on chromosome X. FGFR1 and PROK2/PROKR2 lead to autosomal dominantly inherited type of CHH." (PMID 32222824, 2021). "For instance, besides anosmia/hyposmia, bimanual synkinesia or renal agenesis can associate with ANOS1 mutation." (PMID 32222824, 2021). "Patients with KS associated with ANOS1 pathogenic variants usually exhibit anosmia accompanied with CHH." (PMID 32982993, 2020). "Anosmin-1 is a secreted glycoprotein encoded by the ANOS1 gene, and its loss of function causes Kallmann syndrome (KS), which is characterized by anosmia and hypogonadism due to olfactory bulb (OB) dysfunction." (PMID 31932617, 2020). "ANOS1 was the first gene linked to Kallmann syndrome (KS) and since the early nineties when the first reports demonstrated variants with an X-linked mode of inheritance, many others followed throughout the years." (PMID 32982993, 2020). "ANOS1, formerly called KAL1 gene encodes for anosmin-1 and is responsible for the X-linked form of Kallmann Syndrome." (PMID 31996231, 2020). "The human KAL-1 gene encodes a secreted cell adhesion protein Anosmin-1 and, when mutated, is known to cause Kallmann syndrome, a genetic disease showing various behavioral and neurological defects." (PMID 32973467, 2020). "Loss-of-function variants in ANOS1 were shown to cause the Kallmann syndrome, which is characterized by congenital hypogonadotropic hypogonadism associated with anosmia, delayed puberty and infertility (Dodé and Hardelin, 2009)." (PMID 30747104, 2019). "Mutations in Kallmann Syndrome (KS) genes such as ANOS1 and NSMF, leading to hypogonadotropic hypogonadism with anosmia, have not been found in individuals with self-limited pubertal delay." (PMID 31293522, 2019). "Misexpressing the homolog of KAL-1/anosmin-1, a neural cell adhesion molecule mutant in Kallmann syndrome, in Caenorhabditis elegans causes a highly penetrant, heparan sulfate–dependent axonal branching phenotype in AIY interneurons." (PMID 25098771, 2014).
Kallmann syndrome (continued). "C. elegans kal-1 encodes the homolog of KAL1/anosmin-1, an extracellular matrix protein, which is mutant in patients with the X-linked form of Kallmann syndrome (for review, see Hardelin and Dodé 2008)." (PMID 23451335, 2013). "Anosmin 1 (ANOS1) was the first gene to be associated with Kallmann syndrome (KS)." (PMID 40258767, 2025). "The loss of KAL1/Anosmin-1 could lead not only to olfactory dysfunction, but also to hypogonadotropic hypogonadism, which is observed in Kallmann syndrome." (PMID 38612730, 2024). "In our cohort, four patients (cases 24-25) had a classical clinical picture of Kallmann’s syndrome, but a boy (case 23) with the ANOS1 variant p.Gln586 had increased serum testosterone levels but did not have enlargement of testis after the long HCG test with normal inhibin B and AMH levels." (PMID 35432193, 2022). "Interestingly, the ANOS1 (KAL1) gene, which is an X-linked cause of Kallmann syndrome, was annotated on both the X and Y chromosomes (reference Sscrofa11.1)." (PMID 35550009, 2022). "ANOS1 point mutations and gene deletions are the most common cause of Kallmann syndrome, a rare endocrine disease characterized by both congenital hypogonadotropic hypogonadism (cHH) and hyposmia/anosmia." (PMID 31875237, 2021). "ANOS1 mutations and deletions may explain the phenotype in about 5–10% of cases; in addition to ANOS1, mutations in more than 20 autosomal genes can also lead to Kallmann syndrome." (PMID 31875237, 2021). "ANOS1 was the first gene linked to Kallmann syndrome pathogenesis." (PMID 31996231, 2020). "Mutations of Anosmin 1 (KAL1) and Fibroblast Growth Factor Receptor 1 (FGFR1) lead to Kallmann syndrome, and mutations of the GNRHR and FSHR genes can result in isolated hypogonadotropic hypogonadism." (PMID 41465244, 2025). "Studies on Kallmann syndrome pathogenesis found that anosmin-1 (KAL1 gene) promotes axon outgrowth from the olfactory bulb and the branching into the olfactory cortex." (PMID 38612730, 2024). "Additionally, at early developmental stages, anosmin-1 encoded by the Kallmann syndrome gene (KAL-1) was essential for the differentiation and maturation of olfactory ensheathing cells (OEC) via the FGF2 signaling pathway, which could be blocked by the FGFR inhibitor SU5402." (PMID 37373438, 2023). "Submicroscopic deletions at Xp22.31 lead to the loss of STS (MIM: 300747) and ANOS1 (MIM: 300836) genes, which can cause X‐linked ichthyosis and Kallmann syndrome, respectively." (PMID 32767744, 2020). "A previous study has reported that anosmin-1 encoded by KAL-1, the gene responsible for Kallman syndrome, is involved in LOT development." (PMID 28000762, 2016). "This loss of genes is intriguing since many of them have been demonstrated to be clinically significant to humans; among these are, e.g., SHOX (SHOX homeobox) and ANOS1 (anosmin 1), responsible for the phenotypes of Turner syndrome or Kallmann syndrome, respectively." (PMID 40136496, 2025). "On the other hand, ANOS1 has been linked to Kallmann syndrome, which is characterized by a delayed or absent puberty and impaired olfaction." (PMID 39062680, 2024). "Pathogenic variants in ANOS1 and FGFR1 cause Kallmann’s syndrome." (PMID 35432193, 2022). "However, it is important to note that althoughmutations in ANOS1 typically lead to significant phenotypicanomalies, three family members affected by this mutation only displayed mildsymptoms of hypogonadism without self-observed or clinical manifestations of anosmia(F3, F8, and F9)." (PMID 41165467, 2025). "It was molecularly proven in 25 (8 CHD7 mutations, 6 FGFR1 mutations, 7 ANOS1 mutations, 2 PROKR2 mutations, 1 digenic SOX10/SEMA3F mutation, and 1 digenic ROBO3/IGFS10 mutation with anosmia and later absent puberty)." (PMID 40193582, 2025).
Kallmann syndrome (continued). "Additionally, STK38l is situated within a cryptic translocation site found in patients with Kallmann syndrome, and the ECM molecule ANOSMIN‐1, produced by the KAL1 gene, has been demonstrated to activate β1 integrins." (PMID 40439020, 2025).
hypogonadotropic hypogonadism (21 papers, 2011 to 2025). Abnormal ovarian or testicular function due to insufficient hormonal stimulation from the hypothalamic-pituitary axis. "Congenital central hypogonadism is believed to be caused by genetic pathogenic variants, with genes such as ANOS1, FGFR1, FGF8, PROKR2, and PROK2 being implicated." (PMID 39817151, 2025). "Other rare and novel pathogenic variants in ANOS1, WDR11, FGFR1, RNF216, and CHD7 genes were also found in patients with Congenital Hypogonadotropic Hypogonadism." (PMID 38637882, 2024). "The findings from the present study expand the mutational spectrum of ANOS1 and FGFR1 in hypogonadotropic hypogonadism." (PMID 31996231, 2020). "In human, a proband carrying the nonsense variant R423X in ANOS1, and presenting clinical hypogonadotropic hypogonadism, was also diagnosed with ASD, suggesting a link between ANOS1 and ASD." (PMID 30747104, 2019).
renal agenesis (12 papers, 2011 to 2025). Renal agenesis (RA) is a form of renal tract malformation characterized by the complete absence of development of one or both kidneys (unilateral RA or bilateral RA respectively), accompanied by absent ureter(s). "Further, ANOS1 variants are often associated with other developmental defects, such as renal agenesis, midline defects, hearing impairment and synkynesia, suggesting anosmin-1 is also involved in other developmental processes." (PMID 34502334, 2021). "Approximately 10% of males with ANOS1 pathogenic variants also showed unilateral renal agenesis." (PMID 36859276, 2023). "Preliminary results seem to indicate that anosmin-1 might also affect the chemomigration of embryonic kidney cells (Maggi, in preparation), potentially underpinning its involvement in renal agenesis present in some men with X-linked KS30." (PMID 34046641, 2021). "Anosmin-1 is also expressed in the urinary system from the early steps of kidney development (nephrogenesis), suggesting that the renal aplasia found in X-linked KS20 may result from the agenesis of the metanephros (the developing excretory organ of the foetus)." (PMID 34046641, 2021). "Renal agenesis occurred in 8 of the 20 patients, which may be caused by an ANOS1 deletion." (PMID 32670353, 2020). "Causal P and LP variants were identified in 5 out of 13 patients with a history of cryptorchidism (three in FGFR1, one in ARHGAP5, and one in GNRH1), in 2 out of 8 patients with hearing impairment (CHD7 and FGFR1 genes), and in 2 out of 2 patients with renal agenesis (ANOS1 gene)." (PMID 39308770, 2024). "In total, 2 patients with KS had left renal agenesis (one with an ANOS1 mutation and the other without gene detection)." (PMID 35669683, 2022).
cryptorchidism (11 papers, 2018 to 2025). The failure of one or both testes of a male fetus to descend from the abdomen into the scrotum during the late part of pregnancy. "Loss-of-function variants of the ANOS1 gene lead to KS, and its clinical phenotypes are relatively severe, including complete loss of puberty, infertility, cryptorchidism, and small phallus." (PMID 35090434, 2022). "The incidence of cryptorchidism in patients with FGFR1, ANOS1, and CHD7 mutations is 50–60%, 38.1–66%, and 50–70%, respectively." (PMID 33354214, 2020). "The novel X-linked p.Gln82* in the ANOS1 (KAL1) gene was found in patient 1, a 28-year-old CHH male with pubertal absence, cryptorchidism and micropenis." (PMID 32982993, 2020). "However, two cousins with an ANOS1 LOF variant and with a history of either untreated cryptorchidism, small testicular volume (<4 ml) but normal AMH and inhibin B levels had a good response to HCG treatment." (PMID 35432193, 2022). "Regarding the reproductive phenotype, male KS patients with ANOS1 variants display a complete penetrance of CHH and their pre- and postnatal gonadotropin deficit is severe with a high frequency of micropenis, cryptorchidism and complete absence of gonadal development." (PMID 32982993, 2020).
X-linked Kallmann syndrome (7 papers, 2004 to 2024). "Anosmin-1, the protein implicated in the X-linked Kallmann's syndrome, plays a role in axon outgrowth and branching but also in epithelial morphogenesis." (PMID 17034626, 2006). "Mutations in ANOS1 have been linked to the X-linked Kallmann syndrome." (PMID 38293522, 2024).
gastric cancer (6 papers, 2021 to 2026). A primary or metastatic malignant neoplasm involving the stomach. "Moreover, circulating ANOS1 serves as a diagnostic biomarker for gastric cancer, and the protein is involved in brain tumor malignancies through integrin signaling." (PMID 38293522, 2024). "Moreover, circulating ANOS1 has been identified as a diagnostic biomarker in gastric cancer." (PMID 40529813, 2025). "Gene set enrichment analysis (GSEA) was utilized to determine the functional enrichment of ANOS1 in gastric cancer and the “pRRophetic”R package was utilized to determine the relationship between ANOS1 expression and drug sensitivity." (PMID 40546398, 2025). "The findings revealed a markedly elevated level of ANOS1 expression in advanced gastric cancer tissues relative to adjacent normal tissues (P < 0.001)." (PMID 40546398, 2025). "As a key regulatory factor of gastric cancer, ANOS1 is involved in the metabolic regulation of tumor cells and may have an impact on prognosis and the immune microenvironment." (PMID 41749431, 2026). "The ANOS1 expression and clinical data were acquired from The Cancer Genome Atlas (TCGA) database to analyze the differential expression of ANOS1 and its prognostic impact in advanced gastric cancer." (PMID 40546398, 2025). "ANOS1 may impact gastric cancer progression by regulating EMT, suggesting its dual utility as both a prognostic biomarker and a novel therapeutic target for GC intervention." (PMID 40546398, 2025). "Finally, the correlation between the ANOS1 and immune infiltration in gastric cancer was analyzed." (PMID 41749431, 2026). "The expression of ANOS1 and E-cadherin was detected using immunohistochemical (IHC) techniques in 99 cases of advanced gastric cancer (GC) tissues and their adjacent normal tissues." (PMID 40546398, 2025). "However, the specific role and mechanism of ANOS1 in advanced gastric cancer (GC) and its correlation with epithelial–mesenchymal transition (EMT) are not well understood, despite ongoing research into the expression of ANOS1 and its impact on clinical outcomes." (PMID 40546398, 2025).
congenital hypogonadotropic hypogonadism (4 papers, 2019 to 2025). Congenital hypogonadotropic hypogonadism (CHH) is a rare disorder of sexual maturation characterized by gonadotropin (Gn) deficiency with low sex steroid levels associated with low levels of follicle stimulating hormone (FSH) and luteinizing hormone (LH). "Genes which are associated with congenital hypogonadotropic hypogonadism include : the Fibroblast Growth Factor receptor 1 gene (FGFR), prokineticin receptor 2 gene (PROKR2), GNRH receptor gene (GNRHR) and the Kallmann syndrome 1(KAL1) sequence gene (also known as ANOS-1)." (PMID 38062345, 2024).
hypogonadism (4 papers, 2020 to 2025). A disorder characterized by decreased function of the gonads. "This suggests that a small testicular volume by itself can be considered as unfavorable predictor, which differs from published data and ‘primary’ hypogonadism in GnRH non-responders with ANOS1 variants should not be excluded." (PMID 35432193, 2022).
Obesity (4 papers, 2013 to 2020). Accumulation of substantial excess body fat. "For clinical endocrinologists, symptoms of obesity, strabismus, and ichthyosis should be evaluated in patients with X-linked recessive KS, which may be caused by genes located close to ANOS1." (PMID 32670353, 2020). "We identified a novel 5,807 kb deletion within the Xp22.31-p22.33 regions (chrX: 2700083–8507807) containing STS, ANOS1, and other 24 genes in patient 2, who presented with KS, XLI, obesity, and strabismus." (PMID 32670353, 2020). "We identified a novel 3,923 kb deletion within the Xp22.31 region (chrX: 5810838–9733877) containing STS, ANOS1, GPR143, NLGN4X, VCX-A, PUDP, and PNPLA4 in patient 1, who presented with KS, XLI, obesity, hyperlipidemia, and strabismus." (PMID 32670353, 2020). "Monogenic forms, such as hemizygous ANOS1 mutations or biallelic GnRHR or PROKR2 variants, can explain the more severe phenotypes whereas various combinations of minor IHH alleles with or without acquired factors, such as obesity, can justify the adult-onset of IHH." (PMID 30669598, 2019).
brain tumors (3 papers, 2014 to 2024). "As reactivation of developmental signal pathways often takes part in tumorigenesis, we investigated if anosmin-1-mediated cellular mechanisms associated with brain tumors." (PMID 24189182, 2014). "Therefore, although the normal function of anosmin-1 is required in the proper development of GNRH neurons, overexpression of anosmin-1 in the developed brain may be an underlying mechanism for some brain tumors." (PMID 24189182, 2014). "Although the xenograft models showed evidence of invasion in the presence of anosmin-1, the microenvironment of the brain parenchyma is different from that of flanks, thus the effects of anosmin-1 in brain tumor invasion will need to be reconfirmed in orthotopic models." (PMID 24189182, 2014). "Thus, our gene expression analyses of both public and private datasets support the notion that expression of anosmin-1 correlates with high-grade brain tumors." (PMID 24189182, 2014). "Here anosmin-1, whose function was implicated mainly in the early migratory events of GNRH neurons in the developing brain, is shown to be upregulated in the primary brain tumors, while it remains at low levels in normal brain." (PMID 24189182, 2014). "In summary, the loss-of-function mutations of anosmin-1 disrupt the normal GNRH neuronal development, thus causing KS, but inappropriate activation of anosmin-1-mediated signal pathways in the developed brain is the underlying mechanism of some malignant brain tumors." (PMID 24189182, 2014).